CXCL6 (C-X-C motif chemokine ligand 6)
Diseases named in the same sentence as CXCL6 in open-access papers (continued):
Sharing a sentence is not in itself a finding about the gene and the disease.
Ewing sarcoma (1 paper, 2024). A small round cell tumor that lacks morphologic, immunohistochemical, and electron microscopic evidence of neuroectodermal differentiation. "Moreover, many pediatric neuroblastoma, Ewing sarcoma (ES), osteosarcoma, and ALL, show altered expression of circulating cytokines/chemokines such as CCL2, CXCL4, CXCL6, CXCL10, and CXCL12." (PMID 38927907, 2024).
food allergy (1 paper, 2022). Gastrointestinal disturbances, skin eruptions, or shock due to allergic reactions to allergens in food. "Within these, 113 genes (27.8%) have been previously associated with food allergy; within the top 10 DE genes, 8 genes have been previously linked to food allergy—C3, CXCL8, RARRES1, CXCL6, MUC5AC, CXCL1, and SAA3." (PMID 36452260, 2022).
frontotemporal dementia (1 paper, 2023). Frontotemporal dementia (FTD) comprises a group of neurodegenerative disorders, characterized by progressive changes in behavior, executive dysfunction and language impairment, as a result of degeneration of the medial prefrontal and frontoinsular cortices. "In agreement with the decreased expression in our results, CXCL6 is decreased in the CSF of patients experiencing primary progressive aphasia, a sporadic neurodegenerative disease in the frontotemporal dementia spectrum associated with neuroinflammation." (PMID 37759795, 2023).
fungal infections (1 paper, 2017). "Genes exclusively regulated by atRA during fungal infections included CXCL6 for A. fumigatus challenge, and the fungal pattern recognition receptor Dectin-2 (CLEC6A) as well as the type-I interferons IFNB1 and IFNA14 during C. albicans infection." (PMID 28094291, 2017).
gastroduodenitis (1 paper, 2016). "Cytokines CXCL5 and CXCL6, potent neutrophil chemoattractants, were upregulated in all patients diagnosed with gastroduodenitis." (PMID 28018296, 2016). "Here, we demonstrate upregulation of CXCL5 and CXCL6, potent chemoattractants for neutrophils in serum from juveniles with gastroduodenitis." (PMID 28018296, 2016). "Therefore, we suggest that neutrophil accumulation in tissue in children with gastroduodenitis is directed by a distinct set of chemokines including CXCL5 and CXCL6." (PMID 28018296, 2016).
glaucoma (1 paper, 2011). Increased pressure in the eyeball due to obstruction of the outflow of aqueous humor. "The earlier observations, our finding that CXCL6 expression is affected by PITX2, and that PITX2 mutations can cause glaucoma associated ARS suggest that PITX2 may affect the ARS and glaucoma phenotypes via an effect on the immune response mediated by CXCL6." (PMID 21617755, 2011).
heart failure (1 paper, 2022). Inability of the heart to pump blood at an adequate rate to meet tissue metabolic requirements. "CXCL6 and CXCL8 belong to the cytokine family connected with heart failure and T2DM." (PMID 35663309, 2022).
intra-amniotic infection (1 paper, 2020). "Finally, 26 cytokines [e.g., IFN-γ (log2 FC = 4.9), CXCL6 (log2 FC = 4), and IFN-λ (log2 FC = 3.3), among others] also showed a significant increase in preterm labor with intra-amniotic infection compared to preterm labor with sterile intra-amniotic inflammation." (PMID 31945128, 2020).
leukemia (1 paper, 2013). A malignant (clonal) hematologic disorder, involving hematopoietic stem cells and characterized by the presence of primitive or atypical myeloid or lymphoid cells in the bone marrow and the blood. "We found that CXCL1, CXCL6, TEP1, IL8, CCL2 and PTGS2 genes were the most up-regulated genes in BMSCs co-cultured in the direct contact with leukemia cells." (PMID 24304929, 2013).
liver cirrhosis (1 paper, 2017). "Interestingly, when we re-conducted the GO analysis on overlapping DE genes in liver cirrhosis and HCC (e.g., CCR1, CXCL6, and CXCL12), the results showed that these genes were mainly enriched in the same immune response terms (especially “T cell immune process”)." (PMID 28355233, 2017).
lung disorder (1 paper, 2024). A disease involving the lung. "Considering that CXCL6 expression kept increasing for up to 6 months in the high concentration group in this study, we can conclude that polypropylene may cause lung disorder." (PMID 39107780, 2024).
lymph node metastases (1 paper, 2020). "Comparative analysis of the CXC chemokine/receptor genes revealed significantly higher expression levels of genes encoding ELR+ CXC chemokines/receptors (CXCL1, CXCL3, CXCL6, CXCR1, and CXCR2) in bone metastases relative to lymph node metastases." (PMID 33195424, 2020).
male infertility (1 paper, 2025). The inability of the male to effect fertilization of an ovum after a specified period of unprotected intercourse. "This study establishes a potentially causal relationship between CXCL6 and male infertility, suggesting its potential as a drug target or molecular biomarker." (PMID 40070583, 2025). "Notably, we observed that levels of androstenediol (3beta,17beta) monosulfate, AA-CHOL, and the phosphate-to-glycerol ratio were associated with both CXCL6 and male infertility." (PMID 40070583, 2025). "Using several methods of genetic analyses and Mendelian randomization, we found that circulating CXCL6 may be causally associated with male infertility and have applications as a potential drug target or plasma molecular biomarker in male infertility." (PMID 40070583, 2025). "After FDR adjustment, only C-X-C motif chemokine 6 (CXCL6) was found to have a positive relationship with male infertility (95% CI: 1.7564 to 6.2502, pFDR=0.01966) and considered a significant CIP." (PMID 40070583, 2025). "Our findings identified a significant positive correlation between C-X-C motif chemokine 6 (CXCL6) and male infertility, positioning CXCL6 as a potential therapeutic target or biomarker." (PMID 40070583, 2025). "We estimated the indirect effect of CXCL6 on male infertility via 6 potential mediators, however, the results were not significant." (PMID 40070583, 2025). "Our findings propose that CXCL6 not only warrants in-depth study but also presents potential as both a drug target and a plasma molecular biomarker for male infertility." (PMID 40070583, 2025). "We identified CXCL6 as a promising therapeutic target and possible plasma biomarker for male infertility." (PMID 40070583, 2025). "Collectively, these data suggest that CXCL6 may serve as a plasma molecular biomarker for male infertility." (PMID 40070583, 2025). "The mediation effect of CXCL6 on male infertility via 1400 plasma metabolites." (PMID 40070583, 2025). "Moreover, the CXCL6 detection results was not validated in clinical male infertility patients, and further studies are required to confirm the diagnostic value of CXCL6 and its practical applicability as a biomarker in male infertility." (PMID 40070583, 2025).
malignant rhabdoid tumors (1 paper, 2021). "Using this method, CXCL5/CXCL6 genes were recognized to be overexpressed in malignant rhabdoid tumors." (PMID 33673696, 2021).
myelofibrosis (1 paper, 2022). A partial or complete replacement of the bone marrow stroma by fibrous tissue. "Since CXCR1/CXCR2 are also activated by CXCL6 and MIP2, we may not formally exclude that altered levels of these two chemokines are also involved in the development of myelofibrosis in our model and that their levels where normalized by treatment with Reparixin." (PMID 35392239, 2022).
neuropathy (1 paper, 2023). A disorder affecting the nervous system that manifests with pain, tingling, numbness, and/or muscle weakness. "Importantly, an increased level of CXCL5 is also observed in the CSF of patients with neuropathy, similar to the level of CXCL6, but in rats, after CCI, the CSF level of CXCL6 is not changed." (PMID 37570736, 2023).
osteoporosis (1 paper, 2025). A condition of reduced bone mass, with decreased cortical thickness and a decrease in the number and size of the trabeculae of cancellous bone (but normal chemical composition), resulting in increased fracture incidence. "Firstly, in terms of osteoporosis risk assessment, the 7 inflammatory factors we identified (Artemin, β-NGF, CXCL10, CXCL6, IL-10Rα, IL-10Rβ, LAP-TGFβ1) may become new biomarkers." (PMID 41261570, 2025). "Notably, CXCL6 showed the most significant correlation (P = .0026), which may suggest its important role in the pathogenesis of osteoporosis." (PMID 41261570, 2025).
ovarian carcinoma (1 paper, 2007). A malignant neoplasm originating from the surface ovarian epithelium. "The observed fold changes in gene expression between control (NOSE) and ovarian cancer (EOC) samples were significant (p < 0.01) for CAV 1 (-30.88) and CXCL6 (-4.22) but not significant (p < 0.06) for EMP 3 (+1.10)." (PMID 17254359, 2007).
plague (1 paper, 2016). Plague is a severe bacterial infection caused by the gram-negative bacterium Yersinia pestis. "Many of the genes identified in the present study, such as IL2RG, NdRG, IFNG, and CXCL6, were also regulated in the mouse pneumonic plague models." (PMID 27003632, 2016).
post-traumatic stress disorder (1 paper, 2023). An anxiety disorder precipitated by an experience of intense fear or horror while exposed to a traumatic (especially life-threatening) event. "In individuals with post-traumatic stress disorder (PTSD), there is an increase in serum levels of CCL13, CCL20, and CXCL6, which may indicate a higher risk for developing PTSD." (PMID 37153575, 2023).
rectum adenocarcinoma (1 paper, 2023). An adenocarcinoma arising from the rectum. "In rectum adenocarcinoma, CXCL1 and CXCL3 negatively correlated with EMT, while CXCL5, CXCL6, PPBP, and CXCL8 were positively correlated." (PMID 37686093, 2023).
SARS-CoV infection (1 paper, 2021). "Most were upregulated such as PTGES, MIF, CCR7, CXCL6 and CXCL12, which encodes immune cytokines known to be transcriptionally upregulated during SARS-CoV infection." (PMID 34282405, 2021).
Sciatica (1 paper, 2024). Pain in the lower back and hip radiating in the distribution of the sciatic nerve. "For instance, several key chemokines including CCL2, CCL11, CXCL5, CXCL6, and IL-16 were positively associated with sciatica." (PMID 39015317, 2024).
squamous cell carcinoma (1 paper, 2021). A carcinoma arising from squamous epithelial cells. "In a subsequent study, the master transcription factor SOX2, a lineage-specific oncogene for squamous cell carcinomas, was found to be overexpressed and to promote tumor associated neutrophil (TANs)-accumulation by upregulating CXCL5 (the mouse homolog of human CXCL6) expression." (PMID 33953163, 2021).
stomach adenocarcinoma (1 paper, 2023). "This correlation has been observed in stomach adenocarcinoma with respect to CXCL1, CXCL3, CXCL6, and CXCL8." (PMID 37686093, 2023).
synovitis (1 paper, 2022). Inflammation of a synovial membrane. "Since OA is usually accompanied by synovitis, the secretion of three chemokines (CXCL6, CXCL10, and CXCL16) into the culture medium by HFLS and HFLS-OA was determined." (PMID 36233118, 2022).
systemic sclerosis (1 paper, 2018). A chronic disorder, possibly autoimmune, marked by excessive production of collagen which results in hardening and thickening of body tissues. "In contrast to ERG, the function of FLI1 is less-characterized in ECs; its ablation results in upregulation of CTSL and CXCL6 and downregulation of CXCL5 and CCN1 in the context of systemic sclerosis." (PMID 30500808, 2018).
ulcerative colitis (1 paper, 2025). An inflammatory bowel disease involving the mucosal surface of the large intestine and rectum. "Our results demonstrate that elevated CXCL6 expression correlates significantly with non-response to biologic therapies commonly used in ulcerative colitis (UC), such as Vedolizumab and Infliximab." (PMID 40936930, 2025).
ZIKV infection (1 paper, 2022). "The downregulation of inflammatory genes CCL18, CCL19, CXCL6, CXCL9, IL6R, IL11, IL24, and Integrin Subunit Beta 3 (ITGB3) with ZIKV infection may reflect placental immune tolerance." (PMID 35304593, 2022).
tumor (123 papers, 2007 to 2025). "Secretion of CXCL6 in the tumor microenvironment has been linked to increased tumor-associated neutrophils, which can increase genomic instability via reactive oxygen species, and are recruited by DLBCL cells to promote proliferation." (PMID 41008822, 2025). "The recruitment of the neutrophils in the TME takes place through the release of CXCL5 and CXCL6, with the subsequent transformation of the neutrophils in their pro-tumorigenic phenotype (N2 tumor-associated neutrophils—TANs)." (PMID 38791916, 2024). "Treatment with an anti-murine CXCL6 antibody reduced tumor volume and associated lymph node metastases." (PMID 34503058, 2021). "CXCL6 is principally associated with neutrophil chemotaxis, thereby regulating angiogenesis and immunosuppression that, in turn, promote tumor progression." (PMID 31963450, 2020). "Interestingly, the highly modified chemokine CXCL6 was previously suggested to be associated with local immune suppression and promotion of tumour progression in the immune microenvironment." (PMID 39625179, 2024). "The diverse roles of CXCL6 in various diseases and its involvement in cellular processes and the tumor microenvironment make it a promising drug target for therapeutic intervention in multiple pathological conditions." (PMID 40070583, 2025). "For instance, CAFs-derived cardiotrophin-like cytokine factor 1 (CLCF1) engages ciliary neurotrophic factor receptor (CNTFR) on tumor cells, promoting the release of CXCL6 and TGF-β." (PMID 41445734, 2025). "We subsequently performed in vivo analysis in BALB/c nude mice to assess the function of CXCL6, using sh‐NC or sh‐CXCL6 HuCCT1 cells to focus specifically on its impact on tumor cells." (PMID 40305734, 2025). "CXCR2 is not only activated by CXCL1 but also by several other CXC chemokines, including CXCL2, CXCL3, CXCL5, CXCL6, and CXCL8, all of which are closely associated with cancer progression and the tumor microenvironment." (PMID 40490643, 2025). "Western blot and RT‐qPCR results showed elevated CXCL6 levels in tumor tissues versus paired non‐tumor tissue." (PMID 40305734, 2025). "We used anti‐CXCL2 and anti‐CXCL6 to neutralize the corresponding chemokines in the culture medium of tumor cells." (PMID 39733452, 2025). "While GEM treatment clearly reduced tumor weight and tumor volume, silencing of CXCL6 further enhanced its efficacy." (PMID 40305734, 2025). "Silencing of CXCL6 boosted the efficacy of anti‐PD‐1 therapy, significantly reducing tumor weight and volume." (PMID 40305734, 2025). "The results showed that CXCL6 depletion significantly reduced tumor weight (P < 0.001) and volume (P = 0.001)." (PMID 40305734, 2025). "Sustained inflammatory induction causes the release of Pro-inflammatory cytokines IL-8, Il-17, G-CSF, CXCL5, and CXCL6 from tumor cells and recruitment of neutrophils from the bone marrow to the tumor area, stimulating TAN to develop NETosis." (PMID 38578317, 2024). "CXCL6 is known to promote cell proliferation, angiogenesis, tumor growth, and metastasis in different malignancies, including PCa." (PMID 38017134, 2024). "A recent study reported pathogenic roles of neutrophils in GC through a novel mechanism: tumor tissue can attract neutrophils by CXCL6/CXCL8‐CXCR1 interactions and lead to the accumulation of neutrophils in GC." (PMID 39607202, 2024). "In contrast, in CALB1-expressing tumors, transcription of the same mediators was minimal in cancer cells and instead was found in myeloid cells (CXCL2, CXCL8) and/or tumor-associated fibroblasts (CXCL5, CXCL6)." (PMID 37192000, 2023). "Multiplexed IF staining showed that CXCL6+ tumor cells were located near the SAAs+ hepatocytes in the invasive zone, which highly expressed STAT3 and C-X-C Motif Chemokine Receptor 2 (CXCR2), the receptor of CXCL635." (PMID 37337030, 2023). "The cells which express CXCL6 include tumor cells, fibroblasts, endothelial cells, macrophages, T cells, and neutrophils." (PMID 36831112, 2023).
tumor (continued). "Meanwhile, we also found that CXCL6 was expressed in tumor cells or specific tumor subtype cells in 5 of 7 datasets in TISCH2." (PMID 37491836, 2023). "Accordingly, CXCL6, which can be released by various tumor cells, including HCC cells, is essential for the progression of malignancies." (PMID 37509721, 2023). "Mechanistically, the enhanced expression of SAAs in hepatocytes (Hep1 cells) was induced by activation of the JAK-STAT3 pathway, which was triggered by the secretion of C-X-C Motif Chemokine Ligand 6 (CXCL6) by invasive tumor cells." (PMID 37337030, 2023). "Tumor tissue samples were examined for any relationship between CXCL6/CXCR2 activity and patient prognosis." (PMID 37509721, 2023). "CLCF1, which was made by CAFs, caused tumor cells to make more CXCL6 and TGF-β, which worked on tumor cells to make them more stem-like and on TANs to cause N2 polarization." (PMID 37007004, 2023). "To better understand the association between CXCL6/CXCR2 signaling and the tumor-promoting anti-inflammatory M2 phenotype of TAMs, we used an in vitro coculture system consisting of Huh7 cells and macrophages." (PMID 37509721, 2023). "We characterized an enriched tumor cell cluster (CXCL6+ tumor cells) that featured enhanced EMT, altered metabolic processes, and activated immune responses in this invasive zone compared to other areas." (PMID 37337030, 2023). "CXCL3 acts on the CXCR2 receptor, whereas CXCL6 acts on both CXCR1 and CXCR2 receptors, ultimately resulting in the recruitment of tumor-associated neutrophils and the promotion of tumor angiogenesis." (PMID 37161430, 2023). "Multiple cytokines and chemokines secreted by tumor cells, including IL-8, IL-17, G-CSF, and CXCL6, can recruit bone marrow-derived neutrophils to tumor sites and trigger NETosis." (PMID 36384979, 2022). "It was observed that the release of CXCL6 contributes to recruiting neutrophils loaded with proteases that promote tumor invasion and metastasis." (PMID 36612163, 2022). "Previous studies demonstrated that the miR-431-5p regulated cell proliferation and apoptosis in inflamed tissue, while miR-101-5p inhibited tumor growth by targeting the RAS gene family or CXCL6 axis." (PMID 35634321, 2022). "For instance, the pro-inflammatory cytokines IL-8, IL-17, G-CSF, CXCL5, and CXCL6 are released from tumor cells and recruit neutrophils in the bone marrow to tumor regions." (PMID 35764882, 2022). "CD44, a putative tumor stem cell marker, was significantly associated with C7, CXCL6, CLEC1B, and GPR182 in Hep3B cells and with C7, CXCL6, CLEC1B, and IL1RL1 in Huh7 cells." (PMID 36307751, 2022). "For instance, osteosarcoma cells release EVs carrying membrane-associated TGF-β1, which was shown to educate mesenchymal stromal cells to release CXCL6, and promote further tumor growth and metastasis." (PMID 34567000, 2021). "Tumor cells release cytokines and chemokines such as IL-8, IL-17 and G-CSF, CXCL5 and CXCL6 that attract neutrophils from the bone marrow to tumor sites." (PMID 34261496, 2021). "CAF-derived cardioctonutrient-like cytokine 1 (CLCF1) has been found in studies to stimulate the release of TGF-β and CXCL6 in tumor cells, consequently increasing tumor stem cell development in HCC-TME." (PMID 34869376, 2021). "The results showed that TTCS was superior to NTSC in inducing the migration of tumor‐infiltrating neutrophils, and this effect was almost lost when these neutrophils were pre‐treated with CXCL6/CXCL8 and/or CXCR1 blocking antibodies." (PMID 34185422, 2021). "Here, we investigate the interaction among neutrophils, CD4+ T cells, and tumor cells in tumor tissues, and find that, in GC, neutrophils can be recruited to GC tumors via CXCL6/CXCL8‐CXCR1‐mediated chemotaxis." (PMID 34185422, 2021). "Altogether, these findings support a regulatory model wherein tumor tissues can produce CXCL6/CXCL8 that then recruits neutrophils into the GC environments mediated by CXCL6/CXCL8‐CXCR1 chemotaxis axis." (PMID 34185422, 2021).